MUC1 (mucin 1, cell surface associated)
Diseases named in the same sentence as MUC1 in open-access papers (continued):
Sharing a sentence is not in itself a finding about the gene and the disease.
lung carcinoma (continued). "MUC1 overexpression or depolarized expression also acts as a poor prognostic parameter in lung cancer." (PMID 36367122, 2023). "CRNDE contributes to the resistance to EGFR tyrosine kinase inhibitor in EGFR-mutant lung cancer through eIF4A3/MUC1/EGFR signaling." (PMID 37194105, 2023). "Some exciting target antigens used for generating CAR against lung cancer include MUC-1, CEA, MSLN, HER2, GPC3, ROR1, and EGFR." (PMID 36810079, 2023). "Mucin 1 (MUC1): Glycoprotein MUC1 is overexpressed in several cancers, such as breast, pancreatic, and lung cancers." (PMID 37345057, 2023). "Current antigen targets in clinical trials for CAR-T cell therapy for lung cancer include MUC-1, CEA, HER2, mesothelin, receptor tyrosine kinase-like orphan receptor 1 (ROR1), glypican-3 (GPC3), EGFR, and PD-1." (PMID 37420216, 2023). "Intratumoral and intertumoral heterogeneity in MUC1 expression across diverse types of lung cancer will challenge the strategy of applying AICAR in targeting MUC1-expressing cells." (PMID 36810913, 2023). "Both the overexpression of MUC1 and the depolarized pattern of its expression act as a poor prognostic parameter in lung cancer." (PMID 36367122, 2023). "AICAR represses the MUC1 activity in EGFR-mutant lung cancer, disrupting protein–protein interactions between MUC1-CT and JAK1 and EGFR." (PMID 36810913, 2023). "A phase I trial of the BLP25 (MUC1 peptide) liposomal vaccine in patients with advanced-stage lung cancer established its safety profile and immunogenicity." (PMID 36367122, 2023). "Further, lung cancer cells co-cultured with M2 TAMs significantly increased mucin protein MUC1 and stemness gene expression." (PMID 36550571, 2022). "Some miRNAs found in our analysis that regulate MYOC, KCNQ5, MUC1, and F3 mRNAs has been also described in other cancers, such as colorectal cancer cells and identified as biomarkers in lung cancer, osteosarcoma, ovarian cancer and penile cancer." (PMID 36012492, 2022). "In this work, MUC1 aptamer functionalized PLA-PEG nanocarrier is used for targeted delivery of doxorubicin to MUC1-positive lung cancer cells." (PMID 35304550, 2022). "Mucin-4 is also normally expressed in the lungs and, like MUC1, exerts its oncogenic effects by altering behavior on lung cancer cells." (PMID 35205621, 2022). "Mucin 1 (MUC1) is the most frequently targeted antigen in lung cancer clinical trials, especially for the treatment of NSCLC." (PMID 35455052, 2022). "MUC1-silenced M2-TAMs showed fewer stemness features and concluded that TAMs play an essential role in lung cancer progression." (PMID 36550571, 2022). "Contrarily, MUC1 transcription in SW742 colon cancer and A549 lung cancer cell lines was approximately 103 and 108 times lower than that of fibroblast primary cells, making them to be classified as MUC1‐expressing cell lines." (PMID 34694686, 2022). "HER2, MUC1, and annexin-1 among other autoantibodies as those investigated for early detection of lung cancer." (PMID 36210467, 2022). "The other upregulated genes ELFN2, QSOX1, and MUC1 have been shown to directly promote metastasis in various cancers, including lung cancer." (PMID 34172784, 2021). "Our study verified the high correlation between YBX1 and MUC1 expression in lung cancer for the first time, and the results were consistent with those in large databases." (PMID 34976785, 2021). "In previous studies, YBX1 and MUC1 were crucial in predicting the prognosis and recurrence of lung cancer." (PMID 34976785, 2021). "RNA-seq analysis from Oncomine and TCGA found that YBX1 and MUC1 mRNA expression levels in lung cancer tissues were highly correlated, especially in lung adenocarcinoma." (PMID 34976785, 2021). "Sp-1 has been demonstrated to modulate MUC1 expression by being peculiarly binding on the MUC1 promoter between − 99/− 90 in lung cancer cells." (PMID 32807223, 2020).
lung carcinoma (continued). "A previous study showed that overexpression of MUC1 induces epithelial-mesenchymal transition and promotes the metastasis of lung cancer cells." (PMID 32484849, 2020). "MUC1 has been shown to affect tumor progression in cancers in many organs e.g. a high expression of MUC1 has also been detected in lung cancer." (PMID 32948202, 2020). "The authors conclude in this study that this tumor antigen can elicit a strong immune response and that DC vaccines targeting MUC1, which is expressed in 60% of the lung cancer patients, are a promising immunotherapy in the treatment of cancer." (PMID 33679709, 2020). "Various studies demonstrated that MUC1 plays an important role in drug-resistance, targeted therapy of lung cancer, which makes it an attractive target for lung cancer therapy." (PMID 32807223, 2020). "There are still various transcription factors and signaling molecules regulating MUC1 gene expression in airway epithelial cells and lung cancer cells." (PMID 32807223, 2020). "They developed a cytosensing method by using an aptamer against the protein mucin 1 (MUC1) that is overexpressed in lung cancer." (PMID 32842557, 2020). "In PTX-resistant lung cancer cells, overexposure of MUC1 promotes proliferation, stemness by regulating PI3K/Akt signaling and cancer stemness biomarkers." (PMID 32807223, 2020). "MUC1 plays a key role in TAM-induced in the generation of lung cancer stem cells (LCSCs) progression by regulating NF-κB, CD133, and Sox2." (PMID 32807223, 2020). "Parallel evolution has been shown in a variety of neoplasms, including lung cancers involving genetic alterations in the MUC1, CDK4, CHD8, and NKX2‐1 genes." (PMID 32333643, 2020). "MUC1-targeted vaccines and small molecule drugs are now in clinical studies for preventing lung cancer." (PMID 32807223, 2020). "Pro-oncogenic mucin MUC1 was reported to contribute to smoking-induced lung cancers that are driven by inflammatory signals from macrophages." (PMID 32484849, 2020). "Expression of certain mucins, such as MUC1 or MUC4, have been associated with lung cancer in other studies, and associated with poor prognosis for some patients." (PMID 31429720, 2019). "We anticipate multiple avenues for future research of clinical therapies targeting MUC1 in lung cancer." (PMID 30479696, 2018). "This possible role has spurred the investigation of vaccines directed against MUC1 as an immunomodulatory approach to lung cancer treatment and prevention." (PMID 30479696, 2018). "There is not only a lack of polarization but also altered hypoglycosylation of the MUC1 glycoprotein in lung cancers, which leads to uncovered protein epitopes and greater immunogenicity." (PMID 30479696, 2018). "This is consistent with the rationale for MUC1 as a potential therapeutic target for novel efforts to suppress or prevent the development of lung cancer." (PMID 30479696, 2018). "In conclusion, our results revealed that miR-128 induces apoptosis of paclitaxel-resistant lung cancer cells and decreases MUC1 and stemness-related protein BMI-1 levels." (PMID 29299167, 2017). "Analysis of ONCOMINE database revealed an overexpression of MUC1 in cervical cancer and lung cancer." (PMID 28796259, 2017). "Despite these limitations, the results from our study are quite evocative and provide important insight into the crucial involvement of KL-6/MUC1 in the development of lung cancer and its progression." (PMID 28403862, 2017). "Serum KL-6 levels were significantly associated with the presence of lung ADC, as well as with its progression and prognosis, indicating the crucial involvement of KL-6/MUC1 in the development of lung cancer and its progression." (PMID 28403862, 2017). "We also demonstrated that serum KL-6 levels were significantly associated with the presence of lung ADC and its progression and prognosis, indicating the crucial role of KL-6/MUC1 in the development of lung cancer and its progression." (PMID 28403862, 2017).
lung carcinoma (continued). "Recent studies have shown that MUC1 from TAMs activated the key inflammatory modulator, NF-κB, and contributed to lung cancer development." (PMID 27276704, 2016). "The expression levels of MUC1 and cancer stemness genes significantly increased in lung cancer cells in the presence of the M2-TAM cells." (PMID 27276704, 2016). "Overall, our data support the targeting of MUC1 to reduce PTX resistance via blocking stemness features in lung cancer." (PMID 26779808, 2016). "More importantly, using the PrognoScan software and database, a high MUC1 expression level (n = 63) was found to correlate with a significantly poorer overall survival for patients with lung cancer, compared to patients with lower MUC1 expression (n = 75)." (PMID 27276704, 2016). "Intriguingly, pterostilbene dose-dependently suppressed self-renewal ability in M2-TAMs-co-cultured lung cancer cells, and this suppression was accompanied by downregulation of MUC1, NF-κB, CD133, β-catenin, and Sox2 expression." (PMID 27276704, 2016). "Anti-MUC1 aptamers were developed to selectively deliver Dox or therapeutic plasmid DNA to MUC1 (+) lung cancer cells." (PMID 26863567, 2016). "The A549 NSCLC line was chosen because the cells express lower levels of MUC1 protein compared with other lung cancer cells." (PMID 26779808, 2016). "More importantly, a recent study reported that activated macrophages induce TNF-alpha secretion through PPAR-gamma, ERK, and MUC1 signaling and contribute to smoke-induced lung cancer, establishing a direct involvement of MUC1 in TAM and lung cancer." (PMID 27276704, 2016). "All these findings have provided the experimental basis for targeting MUC1 in patients with diverse carcinomas (breast, prostate, lung cancer, and others with epithelial origin) that express this oncoprotein." (PMID 26112902, 2015). "Since MUC-1 is a marker present on more than 90% of CSCs population covering colon, breast, ovary, prostate, and lung cancers, in situ MUC-1/NK-1 positive expressions of tumor were evaluated." (PMID 26512920, 2015). "Of them, 6 miRNAs (miR-149, miR-205, miR-375, miR-378, miR-422a and miR-708) and 9 target genes (CEACAM6, CGN, CLDN3, ABCC3, MLPH, ACSL5, TMEM45B, MUC1) were validated by quantitative PCR in an independent cohort of 41 lung cancer patients." (PMID 24625834, 2014). "High MUC1 expression in tumors has been correlated with increased invasiveness, migration, and angiogenesis in ovarian and lung cancers." (PMID 23496860, 2013). "Using a novel human MUC1 transgenic (hMUC1.Tg) lung cancer mouse model, we evaluated effects of L-BLP25 combined with low-dose cyclophosphamide (CPA) pretreatment on Th1/Th2 cytokine production and antitumor activity." (PMID 23496860, 2013). "It is possible that consistent stimulation by TNFα secreted from inflammatory cells keeps MUC1 expression in bronchial and alveolar cells at high levels to promote lung cancer development." (PMID 22457794, 2012). "Several MUC1 vaccines are currently in phase 3 clinical trials in patients with breast or lung cancer." (PMID 22586492, 2012). "Likewise, changes in the expression levels of both CLDND1 and MUC1 are associated with the development of lung cancer; it would be interesting to assess the performance of the gene expression model in subjects with other smoking-related diseases such as lung cancer, asthma, and COPD." (PMID 23210427, 2012). "Nevertheless, our results suggest that MUC1 functions as a mediator that bridges CS-induced pulmonary inflammation and lung cancer development by potentiating EGFR-mediated survival signaling." (PMID 22457794, 2012). "MUC1 retained at a high level when cells were transformed, consistent with that MUC1 is constitutively overexpressed in lung cancers." (PMID 22457794, 2012). "As MUC1 potentiates BPDE-induced activation of EGFR, it is likely that MUC1 contributes to lung cancer development at least in part through EGFR-mediated cell survival pathways such as Akt and ERK." (PMID 22457794, 2012).
lung carcinoma (continued). "We characterized MUC1-CD-induced transcriptional changes and examined their significance in lung cancer patients." (PMID 20459602, 2010). "We found increased levels of CRP, SAA, α-1-antitrypsin (AAT) by two distinct antibodies, and MUC1, and decreased levels of transferrin and gelsolin, in lung cancer sera." (PMID 16117833, 2005). "The pattern of increased abundances of CRP, SAA, AAT and MUC1 in lung cancer patient sera that were observed in our microarray-based study is concordant with previous studies of individual proteins." (PMID 16117833, 2005). "Antigens such as Melanoma-associated antigen A1 (MAGE-A1), MAGE-A3, Mucin 1 (MUC1), New York esophageal squamous cell carcinoma 1 (NY-ESO-1) and Epidermal growth factor receptor (EGFR) are some of the main TAAs that use in clinical trials in lung cancer." (PMID 40625850, 2025). "This interplay suggests a feedback loop in which MUC1 not only inhibits immune responses but also actively promotes pathways that protect the tumor from immune clearance, a common characteristic of malignant cells in lung cancer." (PMID 40655139, 2025). "In addition, poor-prognosis tumor types also exhibit nonpolarized MUC1 expression patterns, further illustrating the critical role of MUC1 in the prognostic assessment of lung cancer." (PMID 40655139, 2025). "In lung cancer, high-grade polarized expression of MUC1 is observed in well-differentiated adenocarcinoma, while depolarized MUC1—extending from the apex to the entire surface—is associated with advanced stages, lymph node metastasis, and disruption of cell–cell and cell–matrix interactions." (PMID 40718829, 2025). "The altered localization of MUC1, from its normal restricted patterns to a ubiquitous presence on glandular epithelia and within the cytoplasm, underscores its pivotal role in facilitating lung cancer invasion, metastasis, and angiogenesis." (PMID 40655139, 2025). "Likewise, ACT therapies, including TILs, CAR-T cells, and CAR-NK cells, have shown encouraging activity in targeting lung cancer-associated antigens such as EGFR, MUC1, and mesothelin." (PMID 41394845, 2025). "A proposed five-gene diagnostic signature, including KRT5, MUC1, TREM1, C3, and TMPRSS2, as well as an eight-gene classifier for lung cancer subtypes, exhibited a high predictive accuracy of 0.936 during testing on 2556 adenocarcinoma samples and 1630 squamous cell carcinoma samples." (PMID 38612418, 2024). "The co-expression of EGFR and MUC1 was higher in tumor cells than EGFR combined with targets under active drug development for lung cancer such as MET, HER3 (ERBB3) or Trop2 (TACSTD2), suggesting the potential safety advantage of developing therapies targeting EGFR and MUC1." (PMID 39664199, 2024). "Additionally, future research should investigate the potential applications of the MUC1 promoter in other epithelial cancers, such as ovarian and lung cancers, to augment the clinical utility of CTC detection technologies in cancer screening." (PMID 39886667, 2024). "Lung cancer cells overexpress mucin 1 (MUC1) and active subunit MUC1-CT." (PMID 36810913, 2023). "To investigate the association between ADSL and MUC1 at mRNA levels, we performed a correlation analysis among ADSL and AICAR-binding candidates including MUC1 in six independent datasets consisting of human lung cancer tissues from patients (n = 1418) using Lung Cancer Explorer." (PMID 36810913, 2023). "We were curious if oncogenic EGFR interacts with MUC1-CT in a transgenic lung cancer mouse model." (PMID 36810913, 2023). "MUC1 is overexpressed in lung cancer, making it an excellent target for immunotherapy." (PMID 36367122, 2023). "Several clinical trials of MUC1 vaccines (L-BLP25) in lung cancer have been reported." (PMID 36367122, 2023). "Moreover, an anti-MUC1 DC vaccine showed a significantly prolonged survival among patients with immunohistochemically MUC1-positive advanced or metastatic breast or lung cancer compared to MUC1-negative patients." (PMID 35389164, 2022).
lung carcinoma (continued). "In ALK + lung cancer, there is a higher incidence of MUC1 and MUC5AC cytoplasmic expression, which, combined with a paucity of MUC2 and MUC6 expression, could lead to the biological aggressiveness of ALK + cancer." (PMID 36059804, 2022). "MUC1 is a cell membrane glycoprotein overexpressed in human lung cancer, amongst others." (PMID 35455052, 2022). "Additionally, phase I/II clinical studies in various solid tumors including lung cancer using MUC-1–targeted CAR-T cells have been launched (NCT03525782, NCT02587689)." (PMID 35720364, 2022). "The results showed that the combination of two BsAbs against EpCAM and MUC-1 could inhibit the growth of lung cancer more effectively in cell lines and primary tumors." (PMID 34522164, 2021). "Furthermore, in mouse xenograft models and a lung cancer metastasis model, MUC1, which is downstream of YBX1, partially reversed the decreased number and size of tumors caused by YBX1 silencing." (PMID 34976785, 2021). "Muc-1 aAbs have been detected with prognostic significance in lung cancer, among others." (PMID 34360795, 2021). "Next, we tested whether MUC1 overexpression could rescue lung cancer stem-like properties after YBX1 silencing." (PMID 34976785, 2021). "We previously demonstrated that a deficiency of natural antibodies against CD25, Mucin 1 (MUC1), and vascular endothelial growth factor receptor 1 (VEGFR1) could contribute to high risk of non‐small cell lung cancer (NSCLC)." (PMID 32392378, 2020). "This is the first report to find MUC1 in exosomes of lung cancer cells by LC-MS/MS." (PMID 30646616, 2019). "For this study, we hypothesized that the degree of MUC1 expression increases during the development of human lung cancer, thus serving as an important target of cancerous and precancerous lesions." (PMID 30479696, 2018). "Thus, MUC1 has been a target of interest for vaccine strategies for lung cancer treatment and prevention." (PMID 30479696, 2018). "Previous studies observing the negative association between MUC1 expression and survival in lung cancer were conducted before the recent use of checkpoint inhibitor therapy." (PMID 30479696, 2018). "Although such an approach has not yet been investigated in lung cancer, there has been one study that reported use of a MUC1-based vaccine in patients at high risk for adenocarcinoma of the colon." (PMID 30479696, 2018). "In contrast, the association between rs4072037, a single nucleotide polymorphism in MUC1, and lung cancer has not been well studied." (PMID 28403862, 2017). "Mucin 1 (MUC1) contributes to the growth and metastasis of various cancers, including lung cancer, and MUC1 gene length polymorphisms are associated with susceptibility to lung cancer and its prognosis." (PMID 28403862, 2017). "We hypothesized that MUC1 activation in both lung cancer cells and TAMs may trigger TNF-α mediated signaling events that promote CSC generation." (PMID 27276704, 2016). "TG4010 is a therapeutic lung cancer vaccine targeting MUC1 antigen." (PMID 27686848, 2016). "In agreement, we showed that the treatment of pterostilbene dose-dependently suppressed the percentage of CD133+ lung cancer cells in the presence of TAMs and that this effect was mediated by the concomitant downregulation of MUC1, NF-κB, β-catenin, Sox2, and CD133." (PMID 27276704, 2016). "High-MUC1 expression correlates with invasiveness and a poor prognosis for lung cancer." (PMID 25374843, 2014). "MUC1 classified lung cancer from cancer-free tissue with a failure rate of 2.1%." (PMID 23028920, 2012). "Therefore, it is interesting to determine if MUC1 is also involved in carcinogen-induced EGFR activation for lung cancer development." (PMID 22457794, 2012). "Mucin 1 (MUC1) is a protein heterodimer that is overexpressed in lung cancers." (PMID 20459602, 2010). "We found serum MUC1 levels to be modestly elevated in lung cancer compared to controls." (PMID 16117833, 2005).